ALB (albumin)
Diseases named in the same sentence as ALB in open-access papers (continued):
Sharing a sentence is not in itself a finding about the gene and the disease.
liver fibrosis (continued). "Surrogate markers of liver dysfunction (albumin levels and platelet count) and/or liver fibrosis (LSM) before HCV treatment and LSM regression post-SVR were evaluated to stratify the risk of primary outcomes (LRC or death)." (PMID 34083617, 2021). "Owing to the correlation of TBK1 expression with inflammation indicators (liver fibrosis, platelet-to-albumin ratio), the present study investigated the effects of TBK1 expression on HCC immune infiltration." (PMID 33679751, 2021). "The changes in platelet count after DAA therapy were negatively correlated with baseline PV diameter, stage of hepatic fibrosis, and serum total bilirubin and positively correlated with baseline serum albumin." (PMID 34122539, 2021). "In comparisons of clinical markers, HCC history (−) CNALT patients had higher PLT (P < 0.0001) and albumin (P = 0.002) but lower liver fibrosis marker scores (all P < 0.0001)." (PMID 32782941, 2020). "Here the authors identify the acceptor (A) group as responsible and design a new A group that avoids capture by albumin, and apply it to imaging liver fibrosis in vivo." (PMID 32218438, 2020). "In comparisons of clinical markers between CNALT and non‐CNALT groups, non‐CNALT patients had significantly lower scores for PLT (P = 0.030) and albumin (P = 0.046) but higher scores for liver fibrosis markers (P < 0.05, each) except autotaxin." (PMID 32782941, 2020). "The between-group differences in the hepatic fibrosis grade (p=0.01), serum albumin level (p=0.048), platelet count (p=0.04), and total cholesterol level (p=0.012) were confirmed to be significant." (PMID 33102399, 2020). "This probe effectively prevented albumin interference with improved accuracy for in vivo imaging in a murine liver fibrosis model." (PMID 32218438, 2020). "To validate that pocket-escaping can effectively prevent unwanted fluorescence caused by albumin, we constructed an NIR probe with such feature and tested its efficacy in a murine liver fibrosis model." (PMID 32218438, 2020). "Patients in the Pre‐SVR group were significantly younger (P = .018), had significantly more preserved liver functions, i.e. albumin level (P < .001), platelet count (P < .001); and significantly lower liver fibrosis (P < .001) than those in the Non‐SVR group." (PMID 33319162, 2020). "Conjugation of M6P-modified albumin to hesperidin-loaded liposomes improved the efficacy of chemical drugs and attenuated liver fibrosis." (PMID 33003520, 2020). "One of the major reasons for zinc depletion in hepatic fibrosis and alcoholic liver cirrhosis is decreased serum albumin levels." (PMID 30679730, 2019). "The results of the present study indicate that alteration of trace elements during pathogenesis of hepatic fibrosis is due to metabolic imbalance, biochemical abnormalities, decreased serum albumin, and ascites following NDMA-induced liver injury." (PMID 30679730, 2019). "It has been demonstrated that AGE-bovine serum albumin essentially expanded hepatic fibrosis as proved by expanded collagen content." (PMID 31116779, 2019). "Liver function [aminotransferase (ALT), aspartate aminotransferase (AST), albumin (ALB)] and hepatic fibrosis markers [hyaluronidase (HA), laminin (LN), type III procollagen (PCIII), type IV collagen (CIV)] were measured." (PMID 30810620, 2019). "More recently, albumin-bilirubin (ALBI) grade and the platelet-albumin-bilirubin (PABLI) grade were proposed to evaluate the severity of liver fibrosis in HCC30,31." (PMID 30305679, 2018). "In the present study, the extent of liver fibrosis was estimated from peripheral platelet counts and serum albumin levels at baseline and FIB4 index and serum M2BPGi levels at 4 weeks after the initiation of DCV plus ASV therapy." (PMID 30308053, 2018). "It was reported to have the effects of decreasing transaminase, increasing serum albumin, and preventing liver fibrosis." (PMID 29234362, 2017).
liver fibrosis (continued). "We found that serum albumin., HBsAg, and HbeAg levels were independent predictors of liver fibrosis stage." (PMID 29228729, 2017). "The same authors have proposed a new biomarker, Delta Fibrosis Score, that uses levels of cholinesterase, GGT and albumin combined to age, for prediction of liver fibrosis in HDV infection." (PMID 28329027, 2017). "Regression of liver fibrosis as well as normalization of serum aminotransferase and albumin levels was detected in the rats transplanted with HPCs pretreated with TGF-β1 for 12 hours." (PMID 26839553, 2016). "hADSCs, Ad-huPA and hADSCs/Ad-huPA treatment improves albumin levels, reduces liver fibrosis and diminishes Collagen α1, CTGF and α-SMA mRNA liver levels." (PMID 27992438, 2016). "Previous studies have indicated the preventive and therapeutic effects of CPhGs on bovine serum albumin (BSA)-induced hepatic fibrosis in rats." (PMID 26797590, 2016). "Compared with normal C57BL/6 mice, serum albumin levels were significantly reduced in hepatic fibrosis model mice." (PMID 27022400, 2016). "TAA-induced liver fibrosis rat model markedly decreased normal serum albumin and increased serum ALP and bilirubin levels." (PMID 27275221, 2015). "Mice administered CCl4 for 9 week developed a severe liver injury (AST levels), liver fibrosis (Sirius red staining) and impaired biosynthetic function (reduced albumin levels) (*p<0.05 versus naïve mice)." (PMID 26539823, 2015). "With progression of fibrosis, the decreased ability of hepatocytes to synthesize ALB leads to a decrease in serum ALB concentrations, which is why serum ALB can serve as an indirect indicator of liver fibrosis." (PMID 26088852, 2015). "Serum AIM levels were negatively correlated with platelet count, total cholesterol, and albumin, suggesting that serum AIM levels are potentially associated with hepatic fibrosis and hepatic reserve." (PMID 24524410, 2014). "Univariate analysis revealed that age, platelet count, albumin, ALT, γ-GTP, AIM, and hyaluronic acid were significantly associated with advanced hepatic fibrosis." (PMID 24524410, 2014). "The levels of ALT, AST, alpha-fetoprotein and serum creatinine were significantly higher in group with advanced liver fibrosis while serum albumin and prothrombin were significantly lower in the same group as compared to those with minimal fibrosis." (PMID 27785271, 2014). "The top five molecular function categories were ‘Liver Hyperplasia/Hyperproliferation,’ ‘Increased Levels of Albumin,’ ‘Liver Steatosis,’ ‘Liver Inflammation/Hepatitis,’ and ‘Liver Fibrosis,’ which were complementary to that of the transcriptome." (PMID 25503635, 2014). "Differentiation of BM-MSCs into hepatocytes was determined by immunofluorescence staining using albumin antibody and identification of BM-MSCs in hepatic fibrosis was determined by fluorescent microscopy using CELL STALKER-CSR dye staining." (PMID 25425284, 2014). "Bevacizumab delivery significantly improved albumin (ALB) and glutamine synthetase (GS) levels in rats with hepatic fibrosis." (PMID 24023685, 2013). "According to the “second hit” theory, liver fibrosis was induced with human serum albumin and followed by injection of D-galactosamine/lipopolysaccharide (LPS), resulting in ACLF." (PMID 23874752, 2013). "Multiple regression analysis for prediction of the stage of hepatic fibrosis indicated that CA 19-9, age, alpha-2-macroglobulin, total bilirubin, platelet count and albumin were the most relevant biomarkers related to the stage of hepatic fibrosis." (PMID 24046790, 2013). "Multivariate analysis showed that the most relevant collection of biomarkers for prediction of stage of hepatic fibrosis is: CA 19-9, age, alpha-2- macroglobulin, total bilirubin, platelet count & albumin." (PMID 24046790, 2013).
liver fibrosis (continued). "sIL-2R levels correlated inversely with parameters indicating the hepatic biosynthetic capacity, such as albumin or international normalized ratio, and positively with non-invasive markers of liver fibrosis such as hyaluronic acid or procollagen-III-peptide." (PMID 22530792, 2012). "Furthermore, the degree of liver fibrosis correlated with colonic albumin levels (tau = 0.35, P value = 0.08, Kendall’s rank correlation), suggesting a link between gut barrier dysfunction and liver fibrosis exacerbation." (PMID 41461922, 2026). "Additionally, patients with advanced hepatic fibrosis exhibited notably lower serum albumin compared to those in early stages." (PMID 41026784, 2025). "For example, phenylethanol glycosides from Cistanche tubulosa can prevent rat liver fibrosis induced by bovine serum albumin through the gut microbiota; Si-Ni-San can effectively alleviate liver injury by regulating gut microbiota dysbiosis and enhancing intestinal barrier function." (PMID 39925848, 2025). "Concurrently, liver fibrosis and cholestasis impair albumin synthesis, further reducing AFR." (PMID 41256327, 2025). "This study aimed to investigate the association of LC9 with MASLD and hepatic fibrosis and to reveal for the first time the mediating role of a novel inflammatory marker, neutrophil percentage-to-albumin ratio (NPAR), in the association between LC9 and MASLD." (PMID 40547368, 2025). "Therefore, it is plausible that MSCs therapy can reverse the resulting decrease in serum ALB concentration due to liver fibrosis." (PMID 39104627, 2024). "Furthermore, a modified version of APP (mAPP), a three-math construct constructed using serum albumin level, platelet count, and total bilirubin (T-Bil), is equivalent in its potential to diagnose advanced liver fibrosis and cirrhosis in the previous study." (PMID 38200049, 2024). "We suggest that the hemoglobin, albumin, lymphocyte, and platelet score be used as an additional noninvasive diagnostic tool for autoimmune hepatitis and to predict moderate/advanced liver fibrosis in patients with autoimmune hepatitis." (PMID 38294124, 2024). "In addition, we also observed that levels of albumin, GGT, and cholinesterase were associated with short-term liver fibrosis improvement." (PMID 38808546, 2024). "Previous findings on mammals also confirmed that dietary rutin could effectively increase the levels of serum TP and ALB, and delay the progression of liver fibrosis by down-regulating the expression of transforming growth factor-β1 (TGF-β1) and collagen I." (PMID 37958140, 2023). "Moreover, the abnormal values of albumin and the number of platelets are noted, with a decrease in these biomarkers proportional to the increase in the degree of liver fibrosis." (PMID 38068457, 2023). "Logistic regression analysis showed that globulin, albumin/globulin, GGT levels and anti-Schistosoma IgG were independently associated with liver fibrosis in patients with schistosomiasis and IgG was the largest association of liver fibrosis (OR 2.039, 95% CI 1.293–3.213)." (PMID 37580417, 2023). "EPO attenuated hepatic fibrosis in a dosage-dependent way, as manifested by the diminution in serum alanine aminotransferase and aspartate aminotransferase activities, as well as the increase in albumin level." (PMID 37649466, 2023). "Among patients with advanced liver fibrosis, those with Fuc-Hp ≥ 1700 relative unit, BMI ≥ 23 kg/m2, and albumin < 3.8 g/dL had a significantly higher incidence of HCC than patients not meeting these cutoffs, with a 25% incidence within 3 years and a 55% incidence within 4 years." (PMID 36542633, 2022). "Besides inflammatory responses, increased expression TGF-β and reduced albumin synthesis were found to be synchronized in hepatic regeneration and hepatic fibrosis in a murine model." (PMID 36238273, 2022).
liver fibrosis (continued). "Then, the co-immunofluorescence of hepatocytes marker ALB and Glul showed that Glul expression was expressed limited to 1 layer of perivenous hepatocytes when hepatic fibrosis occurred but Glul expression restored to original level after adopting ADSC-EXO treatment." (PMID 36195966, 2022). "However, our prediction model incorporated new parameters such as blood albumin level, and non-invasive markers of hepatic fibrosis such as nonalcoholic fatty liver disease, fibrosis score, and fibrosis-4 index." (PMID 35789173, 2022). "Albumin platelet product (APP) = Albumin × platelet/1000 could differentiate the four stages of liver fibrosis (p < 0.05)." (PMID 33674669, 2021). "Another earlier study on liver fibrosis models induced by bile duct ligation has shown almost exclusive dexamethasone liposome uptake in Kupffer cells by coupling dexamethasone to mannosylated albumin." (PMID 34298870, 2021). "CK18, TE and ALB were confirmed as independent predictors for liver fibrosis." (PMID 34670509, 2021). "We analyzed the TBK1 expression based on eight widely recognized clinicopathological parameters of the HCC data set from TCGA, including age, gender, alpha-fetoprotein (AFP), tumor stage, tumor grade, T classification, vascular invasion, liver fibrosis, and the value of platelet-to-albumin ratio." (PMID 33679751, 2021). "In another study, dietary glutamine prevented carbon tetrachloride (CCl4)-induced liver fibrosis in mice, reversing many of the CCl4 effects in liver (elevated serum alanine aminotransferase and bilirubin, decreased albumin and increased liver collagen deposition)." (PMID 32825248, 2020). "Furthermore, E-ASCs showed more of a homing ability than ASCs and improved the serum levels of ALT, AST, albumin, total bilirubin and hyaluronic acid more efficient than ASCs in treating CCl4-induced hepatic fibrosis, which was confirmed with histopathology." (PMID 32357508, 2020). "Moreover, compared with free berberine, berberine entrapped in glucose-modified albumin NPs more efficiently inhibited the growth of the human hepatic stellate cell line LX-2 and reduced liver fibrosis in vivo." (PMID 33003520, 2020). "BM-MSCs cultured in the presence of HGF instigate to produce albumin and α-fetoprotein (AFP), and then transplanted MSCs mitigate liver injury in CCl4-induced animal model by restoring serum albumin level and suppressing transaminase activity and liver fibrosis." (PMID 32928306, 2020). "Human serum albumin-dexamethasone NPs were also fabricated to deliver dexamethasone to non-parenchymal hepatic cells, which play an important role in the pathogenesis of liver fibrosis." (PMID 33003520, 2020). "In conclusion, the results of the present study suggest that the modulation of trace elements during pathogenesis of hepatic fibrosis is correlated with metabolic imbalance, biochemical abnormalities, decreased serum albumin, and ascites following NDMA-induced liver injury." (PMID 30679730, 2019). "BCAAs could be more beneficial for advanced liver fibrosis patients whose serum ALB levels are decreased due to reduced mTORC1 signaling in hepatocytes." (PMID 30210344, 2018). "The expression of COL1A1, AFP and ALB are correlated with progression of liver fibrosis." (PMID 30346985, 2018). "A one-time baseline measurement of HBsAg, HbeAg levels and albumin levels could be used to predict liver fibrosis stage in CHB patients with HbeAg seropositive." (PMID 29228729, 2017). "Moreover, when the Lgr5+ cells sorted from the liver fibrosis model were cultured in a differentiation medium (DM), they expressed mature hepatic genes, and abundant amounts of albumin and AAT were secreted into the medium." (PMID 29079780, 2017).
liver fibrosis (continued). "In patients with NAFLD, BGS were significantly correlated with ALB (r = −0.3709, P < 0.05) and the following hepatic fibrosis markers: type IV collagen 7S (r = 0.3556, P < 0.05), P-3-P (r = 0.4796, P < 0.05), the PLT count (r = −0.4114, P < 0.05), and the FIB-4 index (r = 0.3510, P < 0.05)." (PMID 28860506, 2017). "Previous studies have indicated the preventative and therapeutic effects of CPhGs on bovine serum albumin (BSA)-induced hepatic fibrosis in rats, but the antifibrogenic activity of CPhGs and its major monomers (echinacoside and acteoside) have never been evaluated in vitro." (PMID 26797590, 2016). "We next noted significantly higher liver fibrosis indices (p = 0.044), lower mean albumin to globulin ratio (p = 0.0146), and higher serum gamma-GT levels (p = 0.0071) in HIV/HCV co-infected (HIV/HCVc + HIVt/HCVc) subjects compared to HCV mono-infected subjects." (PMID 27455208, 2016). "Therefore, this study aimed to investigate the anti-hepatic fibrosis effect of GPhCs by using a model of bovine serum albumin (BSA) induced hepatic fibrosis in rats." (PMID 26646297, 2015). "Our earlier in vivo work, mouse BM-derived macrophages (and not undifferentiated monocytes) were infused in a murine model of liver fibrosis and resulted in improvement in clinically relevant parameters such as albumin and a reduction in fibrogenesis, demonstrating their therapeutic potential." (PMID 26342993, 2015). "The effect seemed to be related to the mannosylation of serum albumin, because mannosylated serum albumin without dexamethasone also caused increased liver fibrosis." (PMID 26111002, 2015). "In a multivariate regression model including age (≥55 years), platelet count (<17 × 104/μl), albumin (<4.4 g/dl), ALT (≥43 IU/l), γ-GTP (≥27 IU/l), AIM (≥1.2 μg/ml), and hyaluronic acid (≥40 ng/ml), advanced hepatic fibrosis was independently associated with ALT, AIM, and hyaluronic acid." (PMID 24524410, 2014). "Effects of kallistatin on serum AST, ALT and Albumin in CCl4-induced liver fibrosis rats (n = 8)." (PMID 24558397, 2014). "From our previous experimental results, it can be seen that Artesunate can inhibit proliferation of HSC-T6 cell line in 12.5 μg/mL–100 μg/mL, Artesunate (9.6 mg/kg, 28.8 mg/kg, 15 mg/kg orally) can significantly improve rat liver fibrosis induced by CCl4 and bovine serum albumin." (PMID 22053192, 2011). "Clinical parameters, such as aging, albumin level and platelet count, showed a tendency to be related to HCC group 2, indicating that these mutations might occur with liver fibrosis progression." (PMID 22014121, 2011). "In our previous studies, Artesunate could effectually inhibit liver fibrosis in rats induced by carbon tetrachloride or immuned with bovine serum albumin, and proliferation of HSC-T6 cell line." (PMID 22053192, 2011). "As the degree of liver fibrosis increased, albumin, alanine aminotransferase, and platelet count levels gradually decreased; the differences between the groups were statistically significant (P < .05), whereas the degree of liver fibrosis increased with increasing age." (PMID 39470560, 2024). "Furthermore, CCl4-induced liver fibrosis in mice was evaluated by performing liver function tests, including serum ALT and AST, total bilirubin, and albumin to assess liver injury and by performing H&E and Sirius red staining to determine the degree of liver fibrosis." (PMID 36232707, 2022). "Liver enzymes (ALT, AST mainly), synthetic function (albumin and prothrombin time), bilirubin, complete blood count, and platelet count, especially a gradual decline in platelet count, may be more sensitive markers of progressing liver fibrosis." (PMID 33860053, 2021). "Moreover, patients with a more advanced T classification (P = 0.020), severer vascular invasion (P = 0.031), higher degree of liver fibrosis (P = 0.017), and higher value of platelet-to-albumin ratio (P = 0.027) tended to have higher mRNA expression levels of TBK1." (PMID 33679751, 2021).